IL10 (interleukin 10)
Diseases named in the same sentence as IL10 in open-access papers (continued):
Sharing a sentence is not in itself a finding about the gene and the disease.
breast cancer (continued). "Moreover, higher levels of Th2 cytokines—IL-10 and IL-5 —were related to the lack of pathologic complete response after chemotherapy and worse survival in breast cancer patients, respectively." (PMID 31016433, 2019). "The role of IL-10 in tumor biology is controversial; IL-10 is capable of suppressing the cellular immune response and might decrease tumor killing by the immune system, whereas other studies postulated an antitumor activity of IL10 in breast cancer." (PMID 29867524, 2018). "Açaí may modulate the progress of breast cancer by decreasing the presence of the activated macrophages in the tumors, which leads to reductions of VEGF, VEGFR-2, COX-2, PGE2 and IL-10 levels, thereby supporting the use of açaí for an adjuvant treatment together with chemotherapy drugs." (PMID 29609579, 2018). "BMDMs exposed to 4T1 mammary carcinoma-conditioned medium demonstrated enhanced production of pro-inflammatory cytokines tumor necrosis factor α, interleukin-6, and CCL2 in response to lipopolysaccharide (LPS) while production of interleukin-10 remained unchanged." (PMID 26177198, 2015). "For example, breast cancer patients with elevated levels of COX2 and PGE2 within the tumor and the circulation presented T cells with decreased proliferation in response to CD3 antibody stimulation, reduced levels of TNF-α, interleukin (IL)-12, IL-2, and increased levels of IL-10 and IL-4." (PMID 23029485, 2012). "Moreover, the proliferation of the breast cancer cell line BT-474 was not affected by direct treatment with NK20a, indicating that IL-10 might not directly be involved in the proliferation and survival pathways of breast cancer cells." (PMID 38102207, 2023).
Arthritis (318 papers, 2005 to 2026). Inflammation of a joint. "IL-10 therapies in psoriasis vulgaris and associated arthritis were found to be beneficial with good to moderate responses." (PMID 40630332, 2025). "Conversely, a deficiency in IL‐10 can lead to excessive immune cell activation and sustained inflammatory responses, exacerbating arthritis progression." (PMID 39554315, 2024). "In animal models of arthritis, IL-10 deficiency has been demonstrated to result in an elevated production of Th17 and Th1 pro-inflammatory cytokines." (PMID 39125893, 2024). "In the context of Bb infection, IL-10 deficient mice exhibit significantly higher arthritis severity compared to wild type." (PMID 38157387, 2023). "Additional cytokines of C1 included IL-7 (C1L 0.696) and the anti-inflammatory cytokine IL-10 (C1L −0.863); both have been associated with arthritis." (PMID 37047315, 2023). "In AhR-deficient mice, IL-10-producing Breg and regulatory T (Treg) cells are substantially reduced, and arthritis is exacerbated." (PMID 37256149, 2023). "The phosphorylation of p38 MAPK, ERK1/2 and CREB in the late phase of arthritis was associated with increased IL-10 produced by B10 cells." (PMID 36009497, 2022). "The underlying mechanism seems to be in an increase of IL-10 positive regulatory B cells (Bregs), which are capable to remarkably improve the symptoms of arthritis." (PMID 36009497, 2022). "We demonstrate that a loss of gut epithelial cell responsiveness to IL-10 as arthritis develops leads to increased gut permeability and to an exacerbated arthritis." (PMID 34296202, 2021). "In fact, induction of experimental arthritis in Il10-KO mice caused a significant increase in the expression of Nalp3, Aim2 and Caspase-144." (PMID 32385413, 2020). "IL-10-deficient mice display more severe arthritis than wild-type (WT) mice, demonstrating that IL-10 is able to ameliorate IA disease severity." (PMID 33072104, 2020). "In vivo, B cell-specific deletion of AhR caused exacerbated arthritis, reduced IL-10 production by CD19+CD21hiCD24hiBregs, and reduced the frequency of Foxp3+Tregs and expansion of Th1 and Th17 cells." (PMID 31722204, 2019). "In contrast to CH25H, low expression of these CBP enzymes was found to be associated with low IL-10 expression during Th1 switching, and was found to be associated with arthritis development." (PMID 30700717, 2019). "In a model of collagen-induced arthritis it was described that WT CD4+ T cells secrete more IL-17A when cultured with IL-10 deficient B cells." (PMID 31249364, 2019). "B cell AhR-deficient mice develop exacerbated arthritis, show significant reductions in IL-10-producing Bregs and regulatory T cells, and show an increase in T helper (Th) 1 and Th17 cells compared with B cell AhR-sufficient mice." (PMID 31722204, 2019). "Treatment of mice with GRP78 intravenously or subcutaneously during the active phase of the collagen induced arthritis model reduced disease severity and led to increased IL-4, IL-5, and IL-10 (associated with dampening immune responses) production." (PMID 30978945, 2019). "ES-62 antigen isolated from the rodent filarial parasite, A. viteae has the ability to promote the expansion of IL-10-producing B-cells and this was associated with a reduction in the symptoms of arthritis." (PMID 31683524, 2019). "Altogether, these data indicate that loss of HIF-1α in B cells exacerbates arthritis development likely by impairing the IL-10 production by B cells." (PMID 29343683, 2018). "The events that underline the progression of arthritis are mediated by several chemotactic factors such as interleukins (IL-1, IL-6, and IL-10), tumor necrosis factor (TNF-α), interferons (INF-γ) plus leukocytes, and adhesion factors." (PMID 26273477, 2015). "Arthritis in B6 IL-10(−/−) mice has been associated with elevated numbers of T cells, NK cells, and NKT cells as well as macrophage infiltration of the infected joint." (PMID 26497686, 2015).
Arthritis (continued). "In line with an anti-inflammatory role for IL-10 in experimental arthritis, AIA in IL-10KO mice caused increased joint swelling and an overall exacerbation of joint pathology as compared to wild-type (WT) controls." (PMID 25175678, 2014). "The evidence suggests that, in contrast to IL-6, IL-10 plays an active role in ameliorating arthritis caused by degeneration." (PMID 22550538, 2012). "In the systemic plus arthritic stage of SJIA, we found that expression of IL-10 in PBMC was positively associated with arthritis." (PMID 23092393, 2012). "Blocking IL-10 signaling in T cells rendered mice, especially female mice, highly susceptible to collagen-induced arthritis." (PMID 22192790, 2011). "In the arthritis model this effect was associated with down-regulation in IL-6 and IL-12 production and up-regulation of the anti-inflammatory cytokine IL-10." (PMID 19754943, 2009). "This regulatory ability of DNA-HSP65 and its association with higher IL-10 production was already described by our group in experimental arthritis and also in NOD mice." (PMID 19754943, 2009). "Further, in synovial tissue of patients with C. trachomatis associated arthritis, both IL-10 and IFN-γ producing cells were detected and it was suggested that excessive IL-10 production suppresses IFN-γ and mediated persistence." (PMID 18828896, 2008). "The co-administration of heptanoyl CoA (a competitive inhibitor of butyrate synthase) confirmed the contribution of madecassoside-induced butyrate to the anti-arthritis action, as it caused the downregulation of ileum Treg cell number and expression of Foxp3 and IL-10." (PMID 37511889, 2023). "In chimeric mice that had IL-10 knocked-out, specifically in the B cell population, a marked increase in inflammatory Th1 and Th17 cells and enhanced susceptibility to collagen-induced arthritis was observed compared with wild-type B cell chimeric mice." (PMID 35270791, 2022). "Indeed, implication of IL-10-producing T cells [T regulatory 1 (Tr1) cells], Treg and/or IL-10-secreting Breg cells has been shown to be triggered by apoptotic cell infusion in arthritis models and associated with the reduction of joint inflammation." (PMID 33717160, 2021). "These morphological changes were matched by an infiltration of IFNγ-expressing inflammatory leukocytes and a loss of anti-inflammatory IL-10-expressing cells, supporting previous preliminary human studies suggesting that the gut is a site of leukocyte infiltration during arthritis." (PMID 34296202, 2021). "A similar effect was observed in experimental models of encephalomyelitis and arthritis, in which the oral administration of Hsp65-producing L. lactis was shown to prevent disease development in association with increased IL-10 production, as well as in an IL-10-dependent fashion." (PMID 34248935, 2021). "In addition to its role in modulating the severity of chronic experimental arthritis, IL-10 has been linked with anxiety and mood in both rodents and patients." (PMID 37220589, 2016). "This is in contrast to arthritis-susceptible B6 IL10−/− mice, where previously published data show that in addition to upregulation in IL-1β, IL-6, Cxcl1 and Cxcl2, IFNγ and Cxcl10 are upregulated 16-fold and 141-fold at 2 weeks, and 22-fold and 189-fold at 4 weeks, respectively." (PMID 24967703, 2014). "It is tempting to speculate, however, that lack of miR-146a in the arthritis-susceptible C3H mouse would lead to even more severe arthritis, as has been reported in the C3H IL-10−/− mouse model." (PMID 24967703, 2014). "For example, IL-10 inhibits nuclear factor kappa B (NF-κB) signaling in response to TLR agonists to block expression of certain proinflammatory mediators associated with arthritis progression." (PMID 25175678, 2014). "Thus, it is likely that the increased serum levels of IL-10 in estradiol-treated mice contribute to the protective effect of estradiol on clinical development of arthritis as well as on systemic bone loss." (PMID 22507741, 2012).
Arthritis (continued). "Given the immunosuppressive effect of IL-10, association of this gene with arthritis in SJIA may represent an attempt by the immune system to reduce inflammation." (PMID 23092393, 2012). "While it has previously been shown that MSCs transduced to express IL-10 can ameliorate disease and the suppression of arthritis by adipose-derived MSCs was associated with increased synovial IL-10 levels, only a transient increase in this cytokine was demonstrated here." (PMID 22812502, 2012). "A causal relationship between IL-10-producing B cells and Treg cells has been suggested in antigen-induced arthritis model utilizing similar chimeric mice, where loss of IL-10-producing B cells led to significant reduction of Treg cells in draining inguinal LN." (PMID 22347409, 2012). "Studies of RA ST cell cultures indicated that IL-10 may be relatively deficient as compared with proinflammatory cytokines in the joint, and IL-10 has been protective in animal models of arthritis, which suggested its therapeutic potential in human RA." (PMID 16859503, 2006). "Butyrate promotes Treg cell differentiation, and Treg cells produce the anti-inflammatory cytokine IL-10, which further inhibits the production of Th17 cells and ameliorates arthritis." (PMID 41574450, 2026). "Similar findings have been reported in cases of CHIKV-induced arthritis, in which IL-10 appears to play a protective role by reducing inflammatory damage." (PMID 41157617, 2025). "When comparing healthy rams to those with arthritis, the expression levels of the following genes were noticeably higher: IL-1α, IL-1β, IL-6, IL-10, TNFα, NCF4, NFKB, TMED, FCAMR, iNOS and COX18." (PMID 40005882, 2025). "Several studies have highlighted the potential of helminth infections to reduce the severity of arthritis, with the anti-inflammatory cytokine IL-10 emerging as a key mediator of these protective effects." (PMID 41303430, 2025). "We also determined the concentrations of the cytokines IL-6, IL-10, IFNγ, TNFα, IL-17A, IL-17F, and IL-22 in serum samples of the arthritis patients." (PMID 40806470, 2025). "While IL-10 is essential for suppressing arthritis in certain experimental models, its necessity varies depending on the type of helminth and the model of immune-mediated disease." (PMID 41303430, 2025). "Gene expression intensities were much higher in the arthritis-affected rams than in the healthy ones for the genes IL-1α, IL-1β, IL-6, IL-10, TNFα, NCF4, NFKB, TMED, FCAMR, iNOS and COX18." (PMID 40005882, 2025). "IL-17 and IL-10 are balanced in murine Lyme arthritis; the exogenous anti-IL-17 antibody can suppress arthritis." (PMID 40732111, 2025). "The rams with arthritis showed significantly greater levels of gene expression for the genes IL-1α, IL-1β, IL-6, IL-10, TNFα, NCF4, NFKB, TMED, FCAMR, iNOS and COX18 than did the healthy rams." (PMID 40005882, 2025). "Research has verified that the secretion of interleukin-10 by Treg cells in patients with arthritis can ameliorate osteoarthritis." (PMID 40295239, 2025). "Given that sex-based differences in the frequencies of IL-10-producing B cells have been reported in mouse models of arthritis, our goal was to assess B cell-specific IL-10 expression following Mtb infection in a sex-specific manner." (PMID 40260245, 2025). "In experimental arthritis models, Mg supplementation reduced joint damage via microbiome-dependent IL-10 pathways." (PMID 40959529, 2025). "Genetic factors in mice determine cytokine production (notably IL-10 and IFN-γ) and susceptibility to arthritis." (PMID 40732111, 2025). "Flow cytometry analysis revealed an increase of CD19+IgM+CD5+ cell population in draining lymph nodes and an increase of CD19+CD21hiCD23hi (B regulatory) cells in APRIL-Tg mice with arthritis as well as an increase of IL-10 and CXCL13 production in vitro." (PMID 38691538, 2024).
Arthritis (continued). "GMSC‐Exo demonstrated comparable or higher efficacy compared with GMSCs in suppressing the expression of IL‐17A and increasing the expression of IL‐10, thereby reducing the incidence of arthritis and bone erosion." (PMID 38712483, 2024). "In this model, osteostatin reduced the local production of the pro-inflammatory cytokines IL-1β, IL-6, IL-17, and TNF-α, which are increased in patients with arthritis and enhanced the release of the anti-inflammatory cytokine IL-10." (PMID 38474000, 2024). "It will be important to characterize the underlying mechanism of the DUSP6 regulation on IL10 and IL6 expression, as well as DUSP6-specific target signaling pathways in arthritis." (PMID 38974475, 2024). "In AIDs, downregulation of HIF-1α significantly diminishes the number of IL-10-secreting B cells, exacerbating collagen-induced arthritis and EAE." (PMID 39575238, 2024). "In animal studies, SCFAs have been shown to inhibit the onset of arthritis by modulating IL-10 and recent clinical work has shown that progression to the clinical phase of RA is correlated with lower levels of SCFAs." (PMID 38376558, 2024). "One proposed mechanism of action shows that ingested HA binds to toll-like receptor-4 and promotes the expressions of interleukin-10 and cytokine signaling, which both lead to anti-inflammation of arthritis." (PMID 38731044, 2024). "Increased arthritis disease activity was associated with higher levels of inflammatory cytokines (IL-6, TNF and CRP) and immunoregulatory cytokine IL-10 (p<0.05)." (PMID 38507338, 2024). "In our study, we analyzed the effectiveness of using dendritic cells transfected with DNA constructs encoding IL-10, type II collagen, and CCR9 to induce immune tolerance in an experimental model of arthritis." (PMID 39161770, 2024). "While DUSP6 KO mice were again protected in the KSIA model, the IL10 KO and the double KO mice developed severe disease with arthritis scores higher than those of the C57BL/6 WT mice." (PMID 38974475, 2024). "Our study suggests in this cohort with continued mild to moderate clinical arthritis that IL-2 and IL-10 levels are unchanged over time." (PMID 38873035, 2024). "Rats with arthritis showed a marked downregulation of IL-4 (0.405 ± 0.08) and IL-10 (0.309 ± 0.03), indicating that inflammation was successfully induced." (PMID 37111711, 2023). "IL-10 is an important anti-inflammatory and immunosuppressive cytokine that not only prevents the occurrence of arthritis, but also has an inhibitory effect on the development of arthritis." (PMID 37637408, 2023). "Administration of SCFAs to mice with CIA can reduce the severity of arthritis by their ability to increase Foxp3+IL-10–producing Tregs." (PMID 36779190, 2023). "For example, exosomes from IL-10-treated dendritic cells were found to be effective in both suppressing the onset of murine collagen-stimulated arthritis and reducing the symptoms of established arthritis." (PMID 36788505, 2023). "We show that LXA4 reduced TNF-α, IL-1β, and IL-6 levels and increased IL-10 levels in TiO2-induced arthritis." (PMID 37388729, 2023). "B cell-specific deletion of AhR in mice exacerbated arthritis, diminished IL-10 production by Bregs cells, and reduced the frequency of Tregs cells and expansion of inflammatory Th1 and Th17 cells compared with B cell AhR-sufficient mice." (PMID 36779190, 2023). "Further, AhR-dependent IL-10 Breg induction in B cells inhibits GC and plasmablast differentiation and regulates arthritis." (PMID 37256149, 2023). "For example, in the CIA mouse model and RA patients, the HDAC6 selective inhibitor, CKD-L, inhibits IL-6, TNF-α, and IL-1β expression, and increases IL-10 production, resulting in a decreased arthritis score and inhibited proliferation of effector T cells." (PMID 35453416, 2022).